NRIP1 (nuclear receptor interacting protein 1)
Description:
Modulates transcriptional activation by steroid receptors such as NR3C1, NR3C2 and ESR1. Also modulates transcriptional repression by nuclear hormone receptors. Positive regulator of the circadian clock gene expression: stimulates transcription of BMAL1, CLOCK and CRY1 by acting as a coactivator for RORA and RORC. Involved in the regulation of ovarian function (By similarity). Plays a role in renal development.
Synonyms: RIP140; CAKUT3
Tractability: Small molecule: a structure with a bound ligand is known. PROTAC: UniProt records ubiquitination sites on it; ubiquitination databases record sites on it.
Gene: Protein-coding gene on chromosome 21 (14,961,235 to 15,065,936, reverse strand). Ensembl gene ENSG00000180530.
Subcellular location: Nucleus
Subcellular location (Human Protein Atlas): Nucleoli; Nucleoplasm; Cytosol
Pathways (Reactome):
Signal Transduction: Estrogen-dependent gene expression; NR1H2 & NR1H3 regulate gene expression linked to gluconeogenesis; NR1H2 & NR1H3 regulate gene expression linked to lipogenesis
Circadian clock: Expression of BMAL (ARNTL), CLOCK, and NPAS2; RORA,B,C and NR1D1 (REV-ERBA) regulate gene expression
Cellular responses to stimuli: Heme signaling
Metabolism of proteins: SUMOylation of transcription cofactors
Gene Ontology:
Molecular function: nuclear estrogen receptor binding; nuclear glucocorticoid receptor binding; nuclear receptor binding; protein binding; RNA polymerase II cis-regulatory region sequence-specific DNA binding; transcription coactivator activity; transcription corepressor activity; nuclear retinoid X receptor binding; histone deacetylase binding; nuclear retinoic acid receptor binding; signaling receptor binding; transcription coregulator activity
Biological process: cellular response to estradiol stimulus; circadian regulation of gene expression; circadian rhythm; negative regulation of transcription by RNA polymerase II; positive regulation of transcription by RNA polymerase II; lipid storage; ovarian follicle rupture; ovulation; regulation of transcription by RNA polymerase II
Cellular component: chromatin; nucleolus; nucleoplasm; nucleus; histone deacetylase complex; nuclear speck
Genetic constraint (gnomAD): Loss-of-function variants: 28 observed, 78.56 expected, observed/expected ratio (o/e) 0.36, 90% interval 0.26 to 0.49. The upper end of that interval is the gene's LOEUF score, 0.49, which puts it in group 2 of 6, group 1 being the genes least tolerant of losing a copy. Missense variants: 1,435 observed, 1,415.9 expected, observed/expected ratio (o/e) 1.01, 90% interval 0.97 to 1.06. Synonymous variants: 526 observed, 517.67 expected, observed/expected ratio (o/e) 1.02, 90% interval 0.94 to 1.09.
Homologues: Orthologues: chimpanzee NRIP1 (99% identical), macaque NRIP1 (92% identical), rabbit NRIP1 (89% identical), pig NRIP1 (89% identical), guinea pig NRIP1 (88% identical), rat Nrip1 (86% identical), mouse Nrip1 (85% identical), tropical clawed frog nrip1 (50% identical), zebrafish nrip1a (30% identical), zebrafish nrip1b (23% identical).
Diseases named in the same sentence as NRIP1 in open-access papers:
NRIP1 is named in the same sentence as 95 diseases in open-access papers, as found by Europe PMC text mining. Sharing a sentence is not in itself a finding about the gene and the disease. The quoted sentences say what the papers report.
breast cancer (34 papers, 2004 to 2025). A primary or metastatic malignant neoplasm involving the breast. "TNFAIP8 and NRIP1 are mostly associated with tumors, with breast cancer appearing more frequently in our GD network." (PMID 37026010, 2023). "Our in vivo data further suggest that DMBA-induced breast cancer incidence is significantly suppressed in Nrip1 deficient mice compared to wildtype mice." (PMID 26492163, 2015). "The pattern of NRIP1 expression in breast cancer suggests that NRIP1 expression is associated with stromal cells as well as epithelial cells." (PMID 26492163, 2015). "Our results further suggest that 7,12-dimethylbenz[a]anthracene (DMBA) treatment caused up-regulation of Nrip1 in breast cancer tissue from wildtype mice." (PMID 26492163, 2015). "Mutations in NRIP1 have been linked to breast cancer in genome wide association studies." (PMID 33946483, 2021). "Hsa_circ_103110 is encoded by the NRIP1 (nuclear receptor interacting protein 1) gene, the protein product of which stimulates the transcriptional activity of the estrogen receptor and is critical for promoting the progression and development of breast cancer." (PMID 28484086, 2017). "Importantly, a human genome-wide association study found that NRIP1 is significantly associated with the risk of breast cancer." (PMID 26492163, 2015). "Exposure to exogenous estrogens through MHT, which stimulate ER signalling, could therefore alter the association of NRIP1 rs2823093 with breast cancer." (PMID 23544014, 2013). "In contrast, some studies have reported that NOP14 inhibits melanoma by regulating the Wnt/β-catenin pathway and cancer stemness and inhibits breast cancer by inhibiting the NRIP1/Wnt/β-catenin pathway." (PMID 37441804, 2023). "The PGR, ESR1 and CCND1 genes were downregulated when NRIP1 was silenced, indicating the possible role of NRIP1 in breast cancer development." (PMID 34707101, 2021). "Corroborating these studies, our in silico analysis of NRIP1 silencing showed that signaling pathways related to breast cancer were altered." (PMID 34707101, 2021). "Taken together, our results indicate that in the development of breast cancer, NRIP1 is targeted by C-JUN and C-FOS in luminal A cells and plays a role in ductal cell transformation by regulating genes related to the disease." (PMID 34707101, 2021). "To verify the impact of the NRIP1 gene on luminal A breast cancer gene expression, we performed a functional analysis of NRIP1 depletion in the MCF7 cell line using an siRNA approach." (PMID 34707101, 2021). "Another group, using the same approach experiments, revealed that NRIP1 is needed to the regulatory complex required to stimulate breast cancer proliferation." (PMID 34707101, 2021). "For instance, down-regulation of NRIP1 by siRNA inhibited breast cancer cell growth in vitro and in vivo." (PMID 32653032, 2020). "We also found overexpression of NRIP1 in breast cancer cell lines, and that suppression of NRIP1 by siRNA in these cells significantly induced apoptosis and inhibited cell growth." (PMID 26492163, 2015). "To investigate the effects of NRIP1 in breast cancer we used human cell lines and tissue arrays along with an in vivo study of DMBA-induced carcinogenesis in Nrip1 knockout mice." (PMID 26492163, 2015). "Combined, the human breast cancer tissue array results and the DMBA induced mammary tumor data strongly indicates that NRIP1 upregulation is related to breast cancer progression." (PMID 26492163, 2015). "The immunohistochemical assay found that NRIP1 level is elevated both in benign and malignant breast tumors compared to normal tissue adjacent to the tumors." (PMID 26492163, 2015). "The transcription cofactor RIP140 (receptor-interacting protein of 140 kDa), known as nuclear receptor-interacting protein 1 (NRIP1), was first identified in human breast cancer cells through its interaction with the estrogen receptor α." (PMID 25879677, 2015).
breast cancer (continued). "In the current study, we investigated the role of NRIP1 in breast cancer development in order to elucidate the effect of NRIP1 on cell growth, apoptosis and cell cycle arrest." (PMID 26492163, 2015). "Our study reveals that NRIP1 level is elevated in human breast cancer cell lines compared to normal immortalized epithelial cells (MCF10A)." (PMID 26492163, 2015). "Several earlier studies support our recent findings that NRIP1 plays an important role in breast cancer and its development." (PMID 26492163, 2015). "In order to evaluate if NRIP1 influences cell growth, apoptosis and progression of breast cancer, we used human breast cancer cell lines and human breast cancer tissue arrays along with in vivo experiments using Nrip1 deficient mice." (PMID 26492163, 2015). "Specifically in relation to breast cancer, NRIP1 was found to have higher level in luminal-like breast cancer than in basal-like tumors." (PMID 26492163, 2015). "Among these genes, NRIP1, HECA and FIS1 were of particular interest because they have previously been reported to be associated with breast cancer pathogenesis, and further studies of these genes will be pursued." (PMID 24355041, 2013). "Among these genes, NRIP1, HECA and FIS1 were of particular interest since they have previously been reported to be associated with breast cancer pathogenesis." (PMID 24355041, 2013). "Moreover, the genes that changed as a result of NRIP1 knockdown in MCF7 cells were used to stratify patients with breast cancer who received adjuvant tamoxifen treatment." (PMID 34707101, 2021). "We recently reported that NRIP1 was overexpressed in human breast cancer and the suppression of NRIP1 could inhibit growth and induce apoptosis of breast cancer cells." (PMID 27708240, 2016). "Our previous study also showed that in breast cancer cells, suppressing NRIP1 could reduce cells proliferation and induce apoptosis, however, another study found that overexpression of NRIP1 could reduce the proliferation of colon cancer cells." (PMID 27708240, 2016). "Our results indicate that NRIP1 was overexpressed in human breast cancer tissue and cell lines." (PMID 26492163, 2015). "Taken together, our current experimental data suggest that NRIP1 plays an important role in the development of breast cancer and it may be a novel therapeutic target for the treatment of breast cancer." (PMID 26492163, 2015). "However, further detailed studies are needed to validate the specific mechanism of NRIP1 in various types of human breast cancer and its clinical relevance." (PMID 26492163, 2015). "Additionally, in ER-positive breast cancers, NOP14 increases the level of ERα via NRIP1, suggesting an interesting insight for future studies to improve the endocrinotherapy effects on breast cancer patients and lead to better prognosis." (PMID 26213846, 2015). "In order to better understand the importance of NRIP1 in human breast cancers, we first evaluated the expression of NRIP1 mRNA using real-time PCR in three luminal cell lines (ZR75, MCF7, and T47D), five basal or triple negative lines (HCC1806, MX-1, BT20, Hs578T and MDA-MB-231) and one HER2+ line." (PMID 26492163, 2015). "To determine the clinical significance of NRIP1 in breast cancer, we analyzed tissue arrays (US Biomax, Rockville, MD) containing clinical specimens from 75 cases/150 cores, including 138 malignant cores, 6 benign cores and 6 cancer adjacent normal tissue (CANT) cores." (PMID 26492163, 2015). "Our present study suggests that NRIP1 has an important role in cell growth and apoptosis irrespective of cancer types, is associated with luminal, HER2 and basal grade breast carcinomas and is also involved in the progression of chemically induced breast carcinogenesis." (PMID 26492163, 2015).
breast cancer (continued). "NRIP1, a coregulator of several nuclear receptors and transcription factors, can act as a co-activator or corepressor and is upregulated in a variety of tumor types, including gastric cancer, gastric adenocarcinoma (Fang and Lu., 2020), esophageal squamous cell carcinoma, and breast cancer." (PMID 36532732, 2022). "Furthermore, in vivo data suggests that NRIP1 is upregulated in DMBA-induced breast cancer." (PMID 26492163, 2015). "In addition, NRIP1 has been reported negatively correlated with breast cancer through a genome-wide association study (rs2823093; P = 1.1 × 10−12), supporting the possible roles of NOP14 and NRIP1 in breast cancer development." (PMID 26213846, 2015). "Thus, NRIP1 overexpression in breast cancers might also be related to the dysregulation of miR-125b." (PMID 26492163, 2015). "This suggests that NRIP1 may be a novel therapeutic target for the treatment of breast cancer." (PMID 26492163, 2015). "Nuclear receptor-interacting protein 1 (NRIP1), also known as RIP140, was originally identified in breast cancer cells through its interaction with the estrogen receptor α." (PMID 32653032, 2020). "Although GAIT activity has not been demonstrated in other cell types, including breast cancer cells, several genes predicted to be regulated by GAIT, such as RORA, NRIP1, and DZIP3 have been shown to mediate ERα-dependent proliferation of breast cancer cells." (PMID 27612429, 2016). "By using siRNA targeting NRIP1 (siNRIP1), we suppressed NRIP1 expression in 5 breast cancer cell lines (MCF7, T47D, HCC1806, MDA-MB-231 and HCC1954), which includes all three molecular subtypes of breast cancer, and used MCF10A as a control." (PMID 26492163, 2015). "In addition, the nuclear receptor-interacting protein 1 (NRIP1) and the MAPK signaling pathway can regulate the development of breast cancer cells." (PMID 31182966, 2019). "Interestingly, Nrip1 was overexpressed in normal mammary tissue from DMBA treated wildtype mice, indicating that NRIP1 is involved in early stages of the progression of breast cancer." (PMID 26492163, 2015). "Several of the genes involved are also in signalling pathways relevant to breast cancer: ERBB2, NRIP1 and BCAS3 are involved in estrogen receptor function and APPBP2 with androgen receptor; while TAOK1 and SKAP1 are involved in MAPK signalling and DEPDC6/DEPTOR regulates mTOR signalling." (PMID 23260012, 2012). "NRIP1, GREB1, and ABCA3 are all genes found to be ER responsive in at least two cell lines; they have a discernable ERE around the TSS, blocked by ICI and not inhibited by CHX, and their expression can discern ER status in breast cancers." (PMID 15345050, 2004). "Moreover, Western blot analysis of the proteins participating in the Wnt/β-catenin pathway showed that the levels of NRIP1, β-catenin and GSK-3β phosphorylation were elevated by NOP14-overexpressing in three breast cancer cell lines (MDA-MB-231: ER-negative; MCF7 and BT474: ER-positive)." (PMID 26213846, 2015). "Other coding SNPs that could include causal variants producing synthetic associations (associations of rare with common SNPs of high penetrance) include SNPs in genes INS-IGF2, ZFYVE26, C16orf46, UNC13A, NRIP1 and CCDC91 for breast cancer and SNPs in SNED1 and PASK for prostate cancer." (PMID 23555315, 2013). "A number of E2-regulated genes in breast cancer cell lines were not altered by E2 treatment in MOE cells, for example Nrip1." (PMID 26879975, 2016). "By contrast, transwell assays indicated that depletion of NRIP1 by siRNAs in cells with or without NOP14 overexpression promoted the migration and invasion of breast cancer cells." (PMID 26213846, 2015). "Next, an in silico analysis showed that genes related to breast cancer, including HES1, MYC, CCND1, FOS and PGR, could be regulated by NRIP1 (data not shown)." (PMID 34707101, 2021).
Obesity (17 papers, 2010 to 2024). Accumulation of substantial excess body fat. "The only two genes upregulated across all transcriptome-wide PE analyses to date (microarray, RNA-Seq and PAS-Seq) are NRIP1 (RIP140), a transcriptional co-regulator linked to metabolic syndromes associated with obesity, and Flt1." (PMID 28939845, 2017). "NRIP1 is also reported to be prominently related to the pathogenesis of obesity." (PMID 32230784, 2020). "Nrip1 is known to be involved in the development of obesity and diabetes but not with the development of insulin resistance." (PMID 33880624, 2021). "However, body weight and resistance to HFD-induced obesity and hepatic steatosis was only demonstrated in Nrip1−/− mice and Nrip1+/− animals have not been studied." (PMID 22276124, 2012).
colon carcinoma (11 papers, 2014 to 2024). "However, NRIP1 was found as a tumor-suppressor in some other malignancies, such as nasopharyngeal carcinoma, hepatocellular carcinoma, and colon cancer." (PMID 32653032, 2020). "However, a recent study demonstrated a decrease in NRIP1 expression at both transcriptional and translational levels in human colon cancers, which contradicts our recent findings." (PMID 26492163, 2015).
gastric cancer (11 papers, 2017 to 2025). A primary or metastatic malignant neoplasm involving the stomach. "NRIP1 is a nuclear receptor protein, and Its high expression is linked to a bad prognosis of gastric cancer." (PMID 36568182, 2022). "Likewise, the expression level of circ-NRIP1 in gastric cancer tissue and cells was shown to be upregulated." (PMID 33503959, 2021). "In gastric cancer (GC), one study proved that knockdown of the circRNA NRIP1 can suppress the growth of GC cells." (PMID 35352001, 2022). "Circ-NRIP1 acts as a sponge of miR-149-5p in gastric cancer to affect the expression level of AKT1 and ultimately as a tumor promoter in gastric cancer." (PMID 40296904, 2025). "In addition, circ-NRIP1 regulates MYH9 through miR-186-5p to accelerate glycolysis and gastric cancer progression." (PMID 40296904, 2025). "Circ-NRIP1 has been shown to act as a miR-149-5p sponge, thereby suppressing autophagy through the AKT1/mTOR pathway, promoting gastric cancer (GC) cell proliferation and altered energy metabolism." (PMID 35008183, 2021).
esophageal squamous cell carcinoma (10 papers, 2020 to 2025). Esophageal squamous cell carcinoma (ESCC) is a type of esophageal carcinoma (EC) that can affect any part of the esophagus, but is usually located in the upper or middle third. "CircRNA NRIP1 is reported to act as a tumorigenic CircRNA in renal carcinoma and esophageal squamous cell cancer." (PMID 34689819, 2021). "Migration and invasion of esophageal squamous cell carcinoma cells were enhanced upon NRIP1 down-regulation." (PMID 33515271, 2021). "Meanwhile, miR‐576‐5p regulate the migration and invasion of esophageal squamous cell carcinoma cells by inhibiting NRIP1 expression." (PMID 31701656, 2020). "In a study on esophageal squamous cell carcinoma, miR-548-3p and miR-576-5p could promote the migration and invasion of esophageal squamous carcinoma cells by inhibiting NRIP1 expression." (PMID 40345591, 2025). "Upregulated miR-576-5p promotes the migration and invasion of oesophageal squamous cell carcinoma (ESCC) by inhibiting expression of nuclear receptor interacting protein (NRIP1)." (PMID 36618768, 2022). "For instance, circRNA circNTRK2 facilitated the initiation and progression of esophageal squamous cell carcinoma (ESCC) via the miR-140–3p/NRIP1 axis." (PMID 34257535, 2021). "For instance, LncRNA SNHG6 downregulates the miR-101-3p/EZH2 pathway in esophageal squamous cell carcinoma (ESCC), and circNTRK2 promotes cell proliferation, migration, and EMT by sponging miR-140-3p and upregulating NRIP1." (PMID 39944625, 2025).
colorectal cancer (8 papers, 2017 to 2024). A primary or metastatic malignant neoplasm that affects the colon or rectum. "Zhu discovered that NOP14 regulates the NRIP1/GSK-3β/β-catenin signalling pathway to promote colorectal cancer proliferation and migration." (PMID 37441804, 2023).
type 2 diabetes (6 papers, 2007 to 2021). "Nuclear receptor NRIP1 has a pivotal role in lipid and carbohydrate metabolism, indicating the need to investigate subsequent effects of NRIP1 on Type 2 diabetes." (PMID 23776558, 2013).
acute myeloid leukemia (5 papers, 2014 to 2025). Acute myeloid leukemia (AML) is a group of neoplasms arising from precursor cells committed to the myeloid cell-line differentiation. "NRIP1 is a regulator of oncogenic signaling pathways in chronic lymphocytic leukemia and a therapeutic target to sensitize acute myeloid leukemia to all-trans retinoic acid." (PMID 38714703, 2024). "Of note, a recent study identified NRIP1 as a partner of the NRIP1-MIR99AHG fusion in acute myeloid leukemia." (PMID 36600891, 2022). "Few studies have analyzed the deregulation of this gene expression in haematological diseases: NRIP1 has been found to be significantly upregulated in acute myeloid leukemia with complex karyotypes and abnormal chromosome 21." (PMID 24883311, 2014).